SCNN1A (sodium channel epithelial 1 subunit alpha)
Description:
This is one of the three pore-forming subunits of the heterotrimeric epithelial sodium channel (ENaC), a critical regulator of sodium balance and fluid homeostasis. ENaC operates in epithelial tissues, where it mediates the electrodiffusion of sodium ions from extracellular fluid through the apical membrane of cells, with water following osmotically. It plays a key role in maintaining sodium homeostasis through electrogenic sodium reabsorption in the kidneys. Additionally, ENaC is essential for airway surface liquid homeostasis, which is crucial for proper mucus clearance. [Isoform 4]: Not functional.
Synonyms: ENaCA; SCNN1; ENaCalpha; BESC2; LIDLS3; PHA1B1; SCNEA
Tractability: Small molecule: an approved drug acts on it; it belongs to a druggable protein family. Antibody: UniProt places it where antibodies can reach, with high confidence; its Gene Ontology location is reachable by antibodies, with high confidence; UniProt predicts a signal peptide or a membrane-spanning region. PROTAC: UniProt records ubiquitination sites on it; ubiquitination databases record sites on it; a small molecule that binds it is known.
Target class: Ion channel; Ligand-gated ion channel; Epithelial sodium channel
Chemical probes: BI-8668 (high quality)
Gene: Protein-coding gene on chromosome 12 (6,346,843 to 6,383,917, reverse strand). Ensembl gene ENSG00000111319.
Subcellular location: Apical cell membrane; Cell projection, cilium; Cytoplasmic granule; Cytoplasm; Cytoplasmic vesicle, secretory vesicle, acrosome; Cell projection, cilium, flagellum
Subcellular location (Human Protein Atlas): Annulus; Vesicles; Acrosome
Pathways (Reactome):
Sensory Perception: Sensory perception of salty taste
Transport of small molecules: Stimuli-sensing channels
Gene Ontology:
Molecular function: protein binding; sodium channel activity; WW domain binding; ligand-gated sodium channel activity; sodium ion transmembrane transporter activity
Biological process: cellular response to acidic pH; intracellular sodium ion homeostasis; multicellular organismal-level water homeostasis; sodium ion homeostasis; sodium ion import across plasma membrane; sodium ion transmembrane transport; cellular response to aldosterone; cellular response to vasopressin; regulation of blood pressure; sensory perception of salty taste; sensory perception of sour taste; sodium ion transport
Cellular component: apical plasma membrane; ciliary membrane; cytoplasm; extracellular exosome; motile cilium; plasma membrane; sodium channel complex; acrosomal vesicle; sperm principal piece; apical part of cell; cilium; cytosol; external side of plasma membrane; membrane
Genetic constraint (gnomAD): Loss-of-function variants: 58 observed, 65.3 expected, observed/expected ratio (o/e) 0.89, 90% interval 0.72 to 1.11. The upper end of that interval is the gene's LOEUF score, 1.11, which puts it in group 4 of 6, group 1 being the genes least tolerant of losing a copy. Missense variants: 819 observed, 841.85 expected, observed/expected ratio (o/e) 0.97, 90% interval 0.92 to 1.03. Synonymous variants: 329 observed, 349.23 expected, observed/expected ratio (o/e) 0.94, 90% interval 0.86 to 1.03.
Gene-disease validity (ClinGen):
ClinGen rates the evidence that SCNN1A causes each of these diseases.
pseudohypoaldosteronism, type IB1, autosomal recessive (autosomal recessive): Strong.
Homologues: Orthologues: chimpanzee SCNN1A (99% identical), macaque SCNN1A (94% identical), dog SCNN1A (85% identical), pig SCNN1A (84% identical), rat Scnn1a (83% identical), mouse Scnn1a (82% identical), guinea pig SCNN1A (77% identical), rabbit SCNN1A (59% identical), tropical clawed frog scnn1a (55% identical), Caenorhabditis elegans mec-10 (20% identical), Caenorhabditis elegans mec-4 (19% identical), Caenorhabditis elegans acd-2 (18% identical), and 21 more. Paralogues in human: SCNN1D (35% identical), SCNN1G (31% identical), SCNN1B (29% identical), ASIC3 (19% identical), ASIC5 (18% identical), ASIC1 (18% identical), ASIC4 (18% identical), ASIC2 (17% identical).